ENSG00000221611
Synonyms: LOC124903100
Gene: Small nucleolar RNA gene on chromosome 12 (12,972,053 to 12,972,143, forward strand). Ensembl gene ENSG00000221611.
Gene Ontology:
Biological process: RNA processing
Cellular component: nucleolus
Homologues: Orthologues: rat LOC120102741 (64% identical), mouse Gm54541 (56% identical). Paralogues in human: SNORD88C (77% identical), SNORD88A (68% identical), SNORD88B (68% identical).